CRP (C-reactive protein)
Diseases named in the same sentence as CRP in open-access papers (continued):
Sharing a sentence is not in itself a finding about the gene and the disease.
pulmonary hypertension (continued). "The detection of increased concentrations of CRP and Hp may be used to determine a high level of suspicion of pulmonary hypertension in the animals affected, so these APP may be useful as early biomarkers of PH and to stage the disease." (PMID 29143686, 2017). "Therefore, there is potential for use of CRP for staging and monitoring disease in dogs and as an early biomarker of pulmonary hypertension for initial screening of dogs with heartworm disease." (PMID 29143665, 2017). "However, patients with gastrointestinal pathology, pulmonary hypertension, renal disorders, or cholestasis were more likely to have high CRP at BSI onset." (PMID 26259626, 2015). "Therefore, it is reasonable to suppose that the increase in ESR levels may be higher in heartworm-infected dogs with more severe clinical forms (e.g., pulmonary hypertension and caval syndrome), as has been demonstrated for CRP which increases according to the disease severity." (PMID 38560628, 2024). "Noteworthily, there are also several other biomarkers including circulating angiogenic modulatory factors (VEGFR1, CRP, endostatin, or PCEB-ACE) or inflammatory markers (galectin-3, GDF-15) which were related to the pathophysiology of pulmonary hypertension." (PMID 32566097, 2020). "Although serum level of IL-6 has never been studied in dogs with HWD, a recent study found that CRP levels were significantly higher in dogs with HWD and were closely correlated to the severity of pulmonary hypertension." (PMID 29143684, 2017). "In this study we found no statistically improvement in the atorvastatin group compared to the placebo group in SPAH, lung function, CRP, 6MWT in COPD patients with pulmonary hypertension." (PMID 24578830, 2013). "Taken together with increased levels of C-reactive protein (CRP), positive antinuclear, and anti-U1RNP antibodies, she was diagnosed as having mixed connective tissue disease (MCTD) complicating pulmonary hypertension." (PMID 20981316, 2010). "Previous studies have shown that D-dimer and CRP are significant prognostic factors in patients with CTEPH, and arterial oxygen saturation might be a good predictor of the development of pulmonary arterial hypertension." (PMID 38578764, 2024). "A number of factors, such as C-reactive protein (CRP), endothelin-1 and von Willebrand factor may participate in the pathophysiology of pulmonary hypertension." (PMID 24337368, 2014). "Moreover, clinical presentation and other factors including fever, pneumonia, PE, heart failure, acute coronary syndrome, ARDS, septic shock, elevated levels of D-dimer, CRP, BNP, pulmonary hypertension and dilated right ventricle were also predictors of mortality." (PMID 37304946, 2023). "Interestingly, a decrease in HDL was correlated with anti-centromere antibodies and the presence of pulmonary artery hypertension but not with the ESR or CRP level." (PMID 37759971, 2023). "Second, detailed clinical variables such as cardiovascular comorbidity, pulmonary hypertension, inflammatory markers such as CRP, and lung function data were not available from the claim code dataset; therefore, these factors could not be considered in our analyses." (PMID 35402450, 2022). "Moreover, a CRP increase according to the degrees of the disease and a correlation between positive APP such as CRP and the severity of pulmonary arteriola damage and pulmonary hypertension have been also reported, indicating inflammatory processes could contribute to the progression of the disease." (PMID 38560628, 2024). "Moreover, COPD patients with pulmonary hypertension show significantly higher TNF-α and C-reactive protein levels than COPD patients without pulmonary hypertension, further corroborating the role of COPD as an inflammatory systemic disease." (PMID 24739042, 2014).
Shock (61 papers, 2007 to 2026). The state in which profound and widespread reduction of effective tissue perfusion leads first to reversible, and then if prolonged, to irreversible cellular injury. "Cardiogenic shock is associated with systemic inflammation and multiorgan failure; convincing data were obtained on the correlation between shock severity and elevated levels of highly sensitive C-reactive protein, interleukin-1b, interleukin-6, and tumor necrosis factor alpha." (PMID 38137809, 2023). "In pediatric septic shock patients, procalcitonin demonstrated superior predictive capability relative to CRP, a finding consistent with established clinical research." (PMID 40895306, 2025). "This suggests that older patients with higher APACHE II score, SOFA score, CRP, and PCT levels are at a higher risk of mortality from septic shock." (PMID 40638513, 2025). "Patients with septic shock had significantly increased levels of circulating leukocytes and neutrophils, C-reactive protein (CRP), and lactate." (PMID 36917195, 2023). "Neutrophil counts, C-reactive protein, serum ferritin, and procalcitonin levels were significantly elevated in patients with septic shock, whereas lymphocyte counts were significantly reduced." (PMID 36845110, 2023). "Interestingly, these metabolites were also associated with coagulopathy in trauma/hemorrhagic shock, and with microbiome dysbiosis related to iron metabolism, observations informing the correlations in our study between ferritin levels, acute-phase response proteins (CRP), and conjugated bile acids." (PMID 34571942, 2021). "The cut-off value of CRP for diagnosing septic shock was 14.95 mg/dL, with a sensitivity and specificity of 83.3% and 66.7%, respectively." (PMID 25960877, 2014). "Univariate analyses identified low muscle reserve (p < 0.001), high VFA (p = 0.036), high VSR (p = 0.033), age (p = 0.029), PLR (p = 0.029), PT (p = 0.003), INR (p = 0.003), APTT (p = 0.039), D-dimer (p = 0.012), and CRP (p = 0.018) as being potentially independently correlated with septic shock." (PMID 40977984, 2025). "In this study, we found that PCT ≥ 41.47 ug/L and CRP≥222.5 mg/L are independent risk factors for septic shock in patients with DTP, which further confirms that elevated levels of PCT and CRP could predict septic shock in patients with DTP." (PMID 36177334, 2022). "And SAA is correlated with CRP in patients with septic shock." (PMID 34429344, 2021). "However, sCD14 predicted septic shock on day 1 (with area under the curve (AUC) 0.959, 95% CI 0.902–1.000, and p value 0.007) showing a higher AUC for sCD14 than that for CRP or PCT in regard to the development of septic shock." (PMID 28845081, 2017). "In the SSM, baseline CRP levels were similar to those in the SPT (ln(CRP) = 3.36 for an average child with septic shock or MODS); contrary to the SPT, however, the levels reached the maximum slightly later, approximately day 4 (ln(CRP) = 4.43), and decreased less rapidly." (PMID 17598889, 2007). "Similarly, in a larger cohort of patients with cardiogenic shock, admission CRP levels strongly predicted both 30-day and 1-year mortality, with patients in the highest quartile demonstrating more than a two-fold higher risk compared to those in the lowest quartile." (PMID 41552677, 2025). "Our results from the univariate Cox analysis suggested that the presence of septic shock, baselines levels of the SOFA, SAPS III score, lactic acid, CRP, and AFR were six potential prognostic factors for septic patients." (PMID 32454793, 2020). "The combined high-risk category (CD4 < 50 cells/μL and TyG ≥ 9.22) displayed the most severe phenotype, with lower platelet, monocyte, and albumin levels; higher LDH, CRP, and bilirubin concentrations; a mean SOFA score of 6.1; and the highest incidence of septic shock (41.6%)." (PMID 41601726, 2026).
Shock (continued). "Accordingly, SAPS II, SOFA scores and SAPS II based predicted mortality were significantly higher in septic shock-1/2 patients as compared with patients suffering from SIRS, with the same being true for the elevation of C-reactive protein, reflective of the degree of systemic inflammation." (PMID 34972827, 2021). "In patients who did not progress to septic shock, CRP blood levels decreased rapidly after reaching peak values – in contrast to the values in patients with septic shock in whom CRP protein levels decreased slowly." (PMID 17598889, 2007). "As for the prediction of septic shock, hepcidin showed higher sensitivity, specificity, and positive and negative predictive value in diagnosing septic shock compared to HBP, although inferior to CRP and PCT, but the negative predictive value for hepcidin was higher than for PCT." (PMID 36050405, 2022). "Indeed, the patients with septic shock in our cohort had higher C-reactive protein levels than the non-septic patients for the first 48 h of the study." (PMID 29228951, 2017). "Children with PIMS-TS initially often present with signs and symptoms that mimic those of septic shock and toxic shock syndrome and neither clinical findings (fever, rash, abdominal symptoms), infection markers (CRP), nor other laboratory measures of inflammation may allow reliable discrimination." (PMID 34123970, 2021). "Moreover, in patients with septic shock with MODS, changes in CRP and PCT were not related to organ function recovery, while changes in mCD4 levels were closely related." (PMID 38799147, 2024).
tonsillitis (60 papers, 2005 to 2026). Inflammation of the tonsillar tissue. "ESR had an OR of 1.02 (95% CI: 0.97–1.06, p = 0.4), and CRP showed an OR of 1.02 (95% CI: 0.92–1.07, p = 0.6), but neither variable demonstrated a significant association with the diagnosis of tonsillitis." (PMID 39846516, 2024). "In conclusion, low levels of peripheral blood Total FOXP3 mRNA transcript levels are associated with prolonged CRP elevation during active inflammatory responses in incident kidney transplant recipients." (PMID 37771580, 2023). "Our results show that measurements of lower Total FOXP3 mRNA in peripheral blood mononuclear cells, before episodes of inflammatory response, are associated with prolonged elevation of CRP levels in kidney transplant recipients." (PMID 37771580, 2023). "Although we found an association between Total FOXP3 mRNA levels and prolonged CRP elevation during inflammatory responses, this association was found in incident kidney transplant recipients." (PMID 37771580, 2023). "At present, the CRP rs1205 polymorphism is related to prosthetic valve dysfunction in Koreans patients who have undergone mechanical heart valve replacement, which presumably involves inflammatory responses." (PMID 27386381, 2016). "We focussed on a subgroup of patients with FMF in our cohort who exhibited one or more atypical symptoms for FMF, including tonsillitis, lymphadenopathy, aphthous stomatitis, afebrile attacks, and low CRP levels." (PMID 40167786, 2025). "A stepwise multivariable logistic regression was employed to develop the diagnostic model, with the final model retaining age, CA19-9, CEA, disease duration <1 month, C-reactive protein (CRP), surgical history, and lymph node enlargement." (PMID 40678070, 2025). "The main factors that influenced antibiotic prescription rates among all the patients were a younger age (1–4 years), suspected bacterial infection like tonsillitis, CRP values higher than 30 mg/L, as well as CBC or urinalysis test performance." (PMID 38786268, 2024). "Patients who received the diagnosis of tonsillitis had a considerably higher level of immunoglobulin E, a median of 50 IU/mL, the highest levels of C-reactive protein (median of 5.50 mg/L), and an erythrocyte sedimentation rate of 13 mm/h." (PMID 39846516, 2024). "With tonsillitis, a full workup blood test is usually carried out to examine the infection markers (C-reactive protein (CRP), white blood cells (WBC), and lymphocytes), liver and kidney functions, blood cultures, and glandular fever screen." (PMID 38077665, 2023). "Older age, male, lower body temperature, C-reactive protein, and NLR were significant independent risk factors for DNI in patients with tonsillitis." (PMID 37790946, 2023). "Some data revealed elevated CRP in some diphtheria- and mumps-infected cases, yet data are sparse, and also, tonsillitis, peritonsillitis, and peritonsillar abscess cases can have notably elevated CRP values (>100 mg/L)." (PMID 37873776, 2023). "Hemoglobin value was higher in the tonsillitis group, while CRP and ESR values were lower in the tonsillitis group." (PMID 37428978, 2023). "The WBC and CRP levels decreased in comparison to baseline levels at hospitalization, and rapid responses occurred even in patients with kidney transplants who were off the ventilator within a few days and discharged shortly thereafter." (PMID 37760963, 2023). "A study reported that CRP is present mainly in the semen of the infertile than the fertile prostatitis cases, and another study concluded that it is a predictor of failure of the initial management of acute urinary retention in those cases." (PMID 37873776, 2023). "It should be noted that the underlying systemic inflammation was very low in this population of kidney transplant patients with antibody-mediated rejection (median CRP: 2 mg/L)." (PMID 34834375, 2021).
tonsillitis (continued). "In this context, the equivalent values in terms of C-reactive protein stand out, which precludes possible interference by adverse inflammatory conditions (such as prostatitis, for example) on circulating levels of MMPs." (PMID 32425999, 2020). "CRP is of hepatic origin and it is feasible that impaired liver function, which is common in older adults, influenced its production within individuals in the cohort." (PMID 30572949, 2018). "The present study indicated that quantitative plasma proteomics using nano-Liquid-Chromatography-Tandem-Mass-Spectrometry identifies a 82-plex protein signature which predicts increased next-day C-reactive protein in incident kidney transplant recipients." (PMID 26445912, 2015). "Often evolves from tonsillitis; unilateral worsening pain, “hot potato” voice, trismus; may have uvular deviation; CRP often >100 mg/L." (PMID 40933813, 2025). "Notably, 86 (20.1%) children received antibiotics and antibiotic prescription correlated with age, tonsillitis diagnosis, CRP values higher than 30 mg/L, and a CBC of p < 0.05." (PMID 38786268, 2024). "In contrast, for patients with tonsillitis the result of the CRP test reinforced the suspicion of an unspecified bacterial infection, which could overrule the use of the recommended Centor criteria and RADT." (PMID 32031035, 2020). "Further research effort should be performed to identify whether CRP, as a marker of inflammation, plays a direct role in breast carcinogenesis." (PMID 26001129, 2015). "The third cluster (66/1070, 6% of children) is a ‘visibly at risk’ category where children are obese and unfit, and have high blood markers (high trigyceride, CRP), more infections, tonsillitis, vaccinations and more GP visits, and lower educational achievement." (PMID 25074589, 2014). "The first cluster (829/1070, 77% of children) is a ‘low risk’ category where children are not obese, are fit, have normal blood test results (low triglyerides, CRP, fasting insulin, cholesterol), low infection and tonsillitis rates, and average number of GP visits." (PMID 25074589, 2014). "Our findings show that this postprandial lipid profile is specifically related to liver IR, and less so to muscle IR, despite similar body fat percentage, liver fat, and whole-body insulin sensitivity, and lower systemic low-grade inflammation, as indicated by lower circulating CRP levels." (PMID 38493102, 2024). "We performed a prospective study of 91 incident kidney transplant recipients and quantified 359 plasma proteins simultaneously using nano-Liquid-Chromatography-Tandem Mass-Spectrometry in individual samples and plasma C-reactive protein on the index day and the next day." (PMID 26445912, 2015). "First, enhanced renal inflammation may be a mechanism by which CRP promotes diabetic kidney injury." (PMID 24350298, 2013). "Similar tendencies were noted in tonsillitis cases within our study, wherein 97% cases underwent CBC and CRP tests, even though it was contrary to recommendations advocating for a preference of rapid tests." (PMID 38786268, 2024). "Use of CRP and ESR in the model used to differentiate PFAPA and tonsillitis groups with blood markers." (PMID 37428978, 2023). "Regarding inflammatory markers, CRP and ESR, our study revealed significantly higher values in adults with recurrent tonsillitis compared with the control group." (PMID 36600833, 2023). "Markers of kidney inflammation, such as TNFα, IL1β, IL10, F4/80, MCP-1, and CRP, were assessed in total kidney tissues, isolated from both APN-KO and control mice." (PMID 33904399, 2021). "The nomogram showed that CRP/MCV had more prognostic and clinical significance in lymph node-positive patients with poorly differentiated tumors at the late stage." (PMID 34221966, 2021). "And there’s a lot of diseases where there’s no use for CRP... you absolutely don’t need it for sinusitis, you don’t need it for tonsillitis." (PMID 40887118, 2025).
tonsillitis (continued). "As for the inflammatory responses, the WBC count and ferritin levels were higher in the kidney injury group (P < 0.01, respectively), whereas the levels of CRP and IL-6 were not significantly different between both groups." (PMID 39840004, 2024). "In our experience, a similar pattern with major increases in serum CRP but serum ferritin within the reference interval has been observed in dogs with prostatitis or kidney infection by E. coli (data not shown)." (PMID 37344860, 2023). "Hydroxychloroquine is a highly safe immunosuppressant, it can significantly improve the symptoms of dry mouth, dry eyes, arthralgia and other symptoms in patients with Sjogren’s syndrome, and can reduce the erythrocyte sedimentation rate (ESR) and C-reactive protein (CRP), Immunoglobulin (Ig)G, IgM." (PMID 32536964, 2020). "In some CSU patients with coexisting inflammatory processes (e.g. tonsillitis, sinusitis) CRP may be increased, but not D-dimer (unpublished observation)." (PMID 30026764, 2018). "However, in the present study, multivariable analyses showed that use of methylprednisolon did not affect observed increased next-day C-reactive protein in incident kidney transplant recipients." (PMID 26445912, 2015). "For patients with tonsillitis the results of RADT are not fully trusted, but the non-recommended CRP is used as a superior test in line with the outdated idea that a bacterial infection should be detected and treated." (PMID 32031035, 2020). "The use of CRP test is in line with the guidelines for LRTI, but not for tonsillitis." (PMID 32031035, 2020). "Notably, SNPs in CASP1, CRP, IL6R, MYD88, and TLR2 have not been examined for their impact on acute rejection in kidney transplant recipients." (PMID 32153387, 2019).